GAS1 (growth arrest specific 1)
Diseases named in the same sentence as GAS1 in open-access papers (continued):
Sharing a sentence is not in itself a finding about the gene and the disease.
leiomyoma (2 papers, 2007). A well-circumscribed benign smooth muscle neoplasm characterized by the presence of spindle cells with cigar-shaped nuclei, interlacing fascicles, and a whorled pattern. "In contrast, the expression of EGR3, ECM2, THBS1, GAS1 and FBLN5 in scars and RUNX3 and COL18 expression in peritoneal adhesions was higher as compared to leiomyomas." (PMID 17718906, 2007). "A balance between cell growth and apoptosis is critical in progression of tissue fibrosis and the expression of several genes functionally related to these categories, including Bcl-XL, Bad, Bax, p27Kip1, p57Kip2, Gas1, Gas7, CST6, CST7, caspases, etc., were identified in leiomyomas and myometrium." (PMID 17716379, 2007).
microphthalmia (2 papers, 2022 to 2023). Congenital or developmental anomaly in which the eyeballs are abnormally small. "In transgenic mice carrying a targeted mutation in the GAS1 locus, microphthalmia developed: it was histologically revealed that the remnant mutant eyes were ingressed from the surface with minimal RPE and lens, and disorganized eyelid, cornea, and neural retina." (PMID 38203368, 2023). "In addition, mice knocked out for Gas1 exhibit microphthalmia in which the ventral retinal pigmented epithelium is overproliferated and converted into the neural retina." (PMID 35885921, 2022).
osteoporosis (2 papers, 2022 to 2025). A condition of reduced bone mass, with decreased cortical thickness and a decrease in the number and size of the trabeculae of cancellous bone (but normal chemical composition), resulting in increased fracture incidence. "Furthermore, melatonin enhanced osteogenesis of hBMSCs by sponging circ_0003865, repressing miR‐3653‐3p, and leading to Gas1 gene activation and osteoporosis prevention in a mouse model." (PMID 40452254, 2025). "In the context of ovariectomy-induced decreases of melatonin and induction of osteoporosis, the circRNA circ_0003865 was found to sponge the pro-osteogenic miR-3653-3p, which targets Gas1 (growth arrest specific protein 1) mRNA, a factor that blocks osteogenesis." (PMID 35216086, 2022).
arrhythmogenic right ventricular cardiomyopathy (1 paper, 2014). "The RNA expression of RPS6P13 has been reported to bedownregulated in humans for coronary collateralization, while the RNA expression in GAS1 has been reported to be upregulated for arrhythmogenic right ventricular cardiomyopathy in humans." (PMID 25519341, 2014).
atherosclerosis (1 paper, 2023). A disease characterized by the build-up of fatty material and calcium deposition in the arterial wall resulting in partial or complete occlusion of the arterial lumen. "Unlike the reduced expression of Cdon, the expression of other Shh signaling components, Boc, Gas1, and Shh, was also not significantly changed in the transcriptome data from aortas isolated from patients with atherosclerosis and stenosis." (PMID 36609601, 2023).
benign prostatic hyperplasia (1 paper, 2015). A non-cancerous nodular enlargement of the prostate gland. "Similar to what has been reported for GAS-1, immunohistochemical analysis has revealed elevated levels of IBP-3 in the hyperplastic fibromuscular stroma of benign prostatic hyperplasia (BPH) specimens and in the tumor-adjacent stroma of high-grade PCa." (PMID 26110651, 2015).
bladder cancer (1 paper, 2021). "CCK-8 and colony formation assays showed that GAS1 inhibited the viability and proliferation of bladder cancer cells." (PMID 33499877, 2021). "We assessed the effects of GAS1 on bladder cancer cells by constructing stable GAS1-overexpressing cells via lentiviral transduction." (PMID 33499877, 2021). "In addition, both TCGA database analysis and immunohistochemical detection of GAS1 in cohort 2 demonstrated GAS1 dysregulation in bladder cancer." (PMID 33499877, 2021). "Collectively, our results indicate that TAZ, miR-942-3p and GAS1 are novel therapeutic targets that could be exploited for clinical intervention in bladder cancer." (PMID 33499877, 2021). "TAZ, miR-942-3p and GAS1 may be potential therapeutic targets that can be exploited in clinical interventions for bladder cancer." (PMID 33499877, 2021). "Our study identified a novel positive feedback loop between TAZ and miR-942-3p that regulates biological functions in bladder cancer cells via GAS1 expression and illustrated that TAZ, miR-942-3p and GAS1 might be potential therapeutic targets for bladder cancer treatment." (PMID 33499877, 2021). "In summary, the present study verified a novel positive feedback loop between TAZ and miR-942-3p that regulates GAS1 expression and modulates biological behaviors, EMT, glycolysis and intracellular ROS levels in bladder cancer." (PMID 33499877, 2021). "Furthermore, GAS1 and LATS2 were negatively correlated with miR-942-3p in the TCGA database and bladder cancer cell lines at the mRNA and protein levels, respectively." (PMID 33499877, 2021).
breast tumors (1 paper, 2020). "According to TCGA database GAS1 is downregulated in primary breast tumors." (PMID 32050925, 2020).
cleft palate (1 paper, 2016). Cleft palate is a fissure type embryopathy that affects the soft and hard palate to varying degrees. "Ablation of Boc in a Gas1 mutant background leads to reduced Shh activity in the palatal shelves and an increase in the penetrance and severity of cleft palate, associated with failed elevation, increased proliferation and reduced cell death." (PMID 27811357, 2016).
ductal carcinoma in situ (1 paper, 2020). "Comparing pure ductal carcinoma in situ and in-situ component six differentially expressed genes were found, three of them (FGF2, GAS1, and SFRP1), play a role in cell invasiveness." (PMID 32050925, 2020). "We propose these three genes (FGF2, GAS1, and SFRP1) as potential biomarkers of ductal carcinoma in situ progression, suggesting that their downregulation may be involved in the transition of stationary to migrating invasive epithelial cells." (PMID 32050925, 2020).
endometrial disorder (1 paper, 2024). A non-neoplastic or neoplastic disorder that affects the endometrium. "Further investigation into the binding potential of miR-301a-3p with H19 and GAS1 revealed a close association of these genes with endometrial disorders and embryo loss, as per the Comparative Toxicogenomics Database." (PMID 38968269, 2024).
experimental autoimmune encephalomyelitis (1 paper, 2016). An autoimmune demyelinating disease of the central nervous system that is produced experimentally in animals by the injection of homogenized brain or spinal cord in Freund's adjuvant. "We constructed a C. utilis strain, which displays a fusion peptide composed of the encephalitogenic MOG35-55 peptide and the C. utilis Gas1 cell wall protein on its surface.By immunizing mice with MOG35-55 peptide experimental autoimmune encephalomyelitis (EAE) was induced in a mouse model." (PMID 27159446, 2016).
Hypertension (1 paper, 2011). The presence of chronic increased pressure in the systemic arterial system. "GAS1 is a cell cycle inhibiting protein that has been linked to cancer and CSMD1 has been associated with hypertension and peripheral artery disease in GWAS of persons of Asian descent." (PMID 21901158, 2011).
keratoconus (1 paper, 2023). A degenerative, structural disorder of the eye, characterized by a cone-shaped protrusion of the cornea. "An alteration in GAS1 has been revealed for patients with keratoconus (a condition where the cornea becomes progressively thin and protrudes conically)." (PMID 38203368, 2023).
leiomyosarcoma (1 paper, 2018). An uncommon, aggressive malignant smooth muscle neoplasm, usually occurring in post-menopausal women. "WNT9B (17q21.32), S phase entry blocker growth arrest specific 1 (GAS1) and serine/threonine protein kinase D1 (PRKD1) were expressed at low levels in PTSMT while the other analyzed tumor types showed higher levels, in particular, leiomyosarcomas." (PMID 29881541, 2018).
liver failure (1 paper, 2023). A liver disease characterized by the liver losing or has lost all of its function. "In spite of these limitations, we also found a high expression of GAS1 in the APAP-induced liver failure mouse model, suggesting a need to add additional liver failure models for more detailed study." (PMID 37859699, 2023).
liver fibrosis (1 paper, 2016). "In the current study, the Hh-related genes, including Bmp4, Gas1, Gli3, Hhip, Ihh, Prkacb, Stk36, Wnt6, Wnt10b, Wnt9a and Wnt11, were dysregulated in our murine model of CCl4-induced liver fibrosis." (PMID 27322257, 2016). "Although four other Hh-related genes, including Gas1, Prkacb, Stk36 and Wnt9a, were significantly downregulated with the simultaneous upregulation of their regulator miRNAs in the CCl4 group compared to the control group, the roles of these Hh-related genes in liver fibrosis is poorly understood." (PMID 27322257, 2016).
lung carcinoma (1 paper, 2021). "In CRUK0046, we found several genes (FOXN2,GAS1, etc.)in the stem of the phylogeny that are of suggestedimportance for lung cancer initiation, resistance, and metastasis." (PMID 34343239, 2021).
multiple endocrine neoplasia type 1 (1 paper, 2015). An autosomal dominant tumor predisposition syndrome caused by pathogenic variants in the MEN1 gene, characterized by an increased risk of tumors of the parathyroid glands, pituitary gland, and foregut neuroendocrine tumors (most commonly pancreatic islet cells). "Menin, the gene mutated in multiple endocrine neoplasia type 1, recruits the protein arginine methyltransferase 5 (PRMT5) to growth arrest-specific 1 (Gas1) promoter." (PMID 25660620, 2015).
pancreatic adenocarcinoma (1 paper, 2018). "Upregulation of SMO and Hh coreceptors [growth arrest-specific protein 1 (GAS1), brother of CDO (BOC), and cell adhesion molecule-related/down-regulated by oncogenes (CDON)] has been, for example, observed in cancer-associated fibroblasts derived from pancreatic adenocarcinomas." (PMID 29695137, 2018).
rectal cancer (1 paper, 2021). A primary or metastatic malignant neoplasm that affects the rectum. "The results showed that the low expression of GAS1 was negatively correlated with the distribution of CD4+ T cells, CD8+ T cells, macrophages, myeloid dendritic cells (DCs), and neutrophils in both colon and rectal cancer, but positively correlated with B cells." (PMID 33397428, 2021).
scarlet fever (1 paper, 2020). A streptococcal infection, mainly occurring among children, that is characterized by a red skin rash, sore throat, and fever. "This suggests that school is probably a major transmission site for scarlet fever, because children increase their social contacts substantially there, and children are most susceptible to GAS1." (PMID 32843631, 2020).
Sepsis (1 paper, 2024). Sepsis is defined as life-threatening organ dysfunction caused by a dysregulated host response to infection. "Given the previous report of H19 acting as an hsa-miR-301a-3p sponge to mitigate lung injury in sepsis models and the positive correlation we observed between H19 and GAS1 in RIF, we hypothesize that H19 may serve as a ceRNA, regulating GAS1 expression by competitively binding to hsa-miR-301a-3p." (PMID 38968269, 2024).
thyroid cancer (1 paper, 2019). "The mutated TF MZF1 could negatively regulate target gene GAS1, which was also suppressed by MIR34A, to cause the proliferation and suppress the apoptosis of thyroid cancer cells." (PMID 31126066, 2019).
uterine disorder (1 paper, 2024). A non-neoplastic or neoplastic disorder that affects the uterine corpus or the cervix. "The CTD database shows that H19 and GAS1 are associated with uterine disorders, especially embryo loss." (PMID 38968269, 2024).
tumor (47 papers, 1992 to 2025). "While loss of two receptors (Gas1 and Boc) promote tumor growth, deleting all three co-receptors reduces tumor growth." (PMID 35867772, 2022). "In several studies, GAS1 was reported a tumor suppressor and its downregulation associated with cancer progression and poor survival prognosis." (PMID 33990633, 2021). "Several studies have implicated the sonic hedgehog (SHH) pathway in Gas1-mediated tumor growth inhibition." (PMID 30327548, 2018). "This additional activation of SMO receptors (together with the mutated PTCH1 or SMO genes) could improve the tumour’s ability to resist some of the inhibition caused by Vismodegib, explaining the high GAS1 levels in the partially responsive laBCCs." (PMID 31988301, 2020). "Additionally, microarray analysis showed that transfection with Gas1 causes the expression of many liver genes to revert to their non-tumor level." (PMID 26161998, 2015). "In vivo mouse-based experiments have also confirmed higher mRNA levels of GAS1 in tumor tissues than those in normal tissues." (PMID 39726813, 2024). "Studies have supported GAS1 functioning as a tumor or metastasis suppressor protein in a number of human cancers, including lung carcinoma, bladder carcinoma, gastric cancer, gliomas, melanoma, and CRC20–24." (PMID 38816533, 2024). "The data for 48 primary tumor samples indicated that GAS1 mRNA and protein expression levels were significantly reduced in tumor tissues." (PMID 37824217, 2023). "GAS1 can inhibit the proliferation of malignant tumor cells and promote apoptosis in cancers of the rectal wall and melanoma." (PMID 37859699, 2023). "We found that ATOH1 mRNA expression levels were positively correlated with GAS1 in 48 primary tumor samples (P < 0.001)." (PMID 37824217, 2023). "The tumor-targeting capabilities and overall biodistribution patterns of GAS1/2/3-radioligands were studied in immunosuppressed mice bearing a twin xenograft model, namely subcutaneous tumors from either HEK293-CCK2i4svR or wtHEK293 cells." (PMID 35336041, 2022). "Concordant with these findings, [177Lu]Lu-GAS3 showed higher HEK293-CCK2i4svR tumor-targeting capacity compared with [177Lu]Lu-GAS1 at all time intervals." (PMID 35336041, 2022). "These patterns of tumor growth in Gas-/-;Boc-/- and Gas1-/-;Boc-/-;Cdon-/- tumors also coincide with increased and decreased vasculature, respectively, indicating that subtle differences in HH signaling levels impact multiple compartments within the TME." (PMID 35867772, 2022). "It is evident that the pendant (radio)metal-chelate has a strong impact not only on receptor affinities and cell uptake but, most importantly, on the tumor-targeting capabilities and overall pharmacokinetic profile of tested GAS1/2/3-radioligands." (PMID 35336041, 2022). "The present study revealed a few promising features with regards to the application of [177Lu]Lu-GAS1/3 as anti-CCK2R tumor therapeutics." (PMID 35336041, 2022). "Based on the results of DEGs survival analysis, we further investigated the relationship between GAS1 and immune cell infiltration in tumor tissues." (PMID 33397428, 2021). "Immunochemical assays and western blotting indicated that TAZ knockdown upregulated the levels of LATS2 and GAS1 in tumor tissue and that miR-942-3p reversed these trends." (PMID 33499877, 2021). "In the infiltration analysis of immune cells in tumor tissues, it can be found that the expression level of GAS1 is related to the infiltration distribution of various immune cells." (PMID 33397428, 2021). "Further exploration of GAS1 revealed that its expression was interrelated with the infiltration of immune cells in tumor tissues." (PMID 33397428, 2021). "Division of the laBCC group by partial or complete response to treatment showed that a single gene, GAS1, was predictive of the tumour response." (PMID 31988301, 2020).
tumor (continued). "‘The tumor suppressor effects of GAS1 had been previously reported in cell cultures or in xenograft models, this is the first work in which the suppressor activity of murine Gas1 is reported for primary tumors in vivo." (PMID 32663221, 2020). "In conclusion, this study has identified Gas1 as a novel factor and mechanism through which microglia arrest the growth of BTICs for anti-tumor property." (PMID 30327548, 2018). "The high DE tumor suppressor miRNA-449-A inhibits proliferation and prevents metastasis, and regulates the co-expressed GAS1 (putative tumor suppressor) and CDK4." (PMID 28824643, 2017). "The top differential edges of this network included at least two tumor suppressor genes (GAS1 and CD9)." (PMID 28506242, 2017). "The potential role of GAS1 as a tumor suppressor was studied by analyzing tumor progression after the implantation of Gas1-overexpressing malignant cells in mice." (PMID 26161998, 2015). "It has been described that overexpression of Gas1 is able to reduce the tumor volume due to both, inhibition of cell proliferation and induction of apoptosis." (PMID 26161998, 2015). "Although the tumor suppressor effects of GAS1 had been previously reported in cell cultures or in xenograft models, this is the first work in which the suppressor activity of murine Gas1 is reported for primary tumors in vivo." (PMID 26161998, 2015). "Animals from groups T (after tumor) and G (after Gas1) received an intraperitoneal injection of DEN 15 days after birth, while those of the C (after control) group were injected with saline as a DEN-negative, control group." (PMID 26161998, 2015). "We observed other markedly under-expressed genes (P<0.05) included tumour-suppressor candidates that negatively regulate the Hh pathway (SUFU, GAS1, RAB23) and genes encoding inhibitory proteins (HHIP, HHAT)." (PMID 22361633, 2012). "Among these growth arrest-specific (Gas) genes, only Gas1 demonstrated the ability to inhibit cell proliferation when over-expressed in normal and transformed cell lines, and to reduce tumor cell growth." (PMID 21858068, 2011). "On the other hand, over-expression of Gas1 inhibits cell proliferation in different tumor cell lines, as well as in cultured fibroblasts and, recently, the possible benefits of Gas1 in tumor gene therapy have been advanced." (PMID 21858068, 2011). "Expression of c-myc was also evaluated and found to be high in tumours which exhibited low gas-1 expression." (PMID 1379061, 1992). "Despite its role as a tumor suppressor, few regulators of GAS1 expression have been identified." (PMID 38816533, 2024). "GAS1 upregulation reduced the tumor initiation capacity of SNU‐5‐shATOH1 cells." (PMID 37824217, 2023). "GAS1 may be a negative regulator of the Hedgehog signaling pathway, in order to regulate tumor proliferation and differentiation, angiogenesis, invasion, migration, and apoptosis of cells and other functions by regulating the Hh pathway." (PMID 36743693, 2023). "Furthermore, growth arrest specific 1 (GAS1) inhibits the cell cycle progression from G0 to the S phase, which inhibits tumor progression and plays an anticancer role." (PMID 36743693, 2023). "Gas1 negatively regulates glycolysis and provides energy for tumor progression and metastasis." (PMID 36843929, 2023). "Compared with the previously reported biodistribution data of [99mTc]Tc-DGA1 in the same animal model, we observed a much higher tumor to kidney ratio for all [67Ga]Ga/[111In]In/[177Lu]Lu-GAS1/3 radioligands and an overall improvement of the pharmacokinetic profiles." (PMID 35336041, 2022). "Thus, concordant with biodistribution findings, these results reveal that tumor uptake of [111In]In-GAS1/2/3 is a CCK2i4svR-mediated process." (PMID 35336041, 2022). "The result showed that the anti-tumor effect of GAS1 could be superimposed with the inhibitory effect of PTEN on Akt pathway, and this could significantly inhibit the growth of GBM." (PMID 34055646, 2021).